E2F1 (E2F transcription factor 1)
Diseases named in the same sentence as E2F1 in open-access papers (continued):
Sharing a sentence is not in itself a finding about the gene and the disease.
melanoma (105 papers, 2003 to 2026). A malignant, usually aggressive tumor composed of atypical, neoplastic melanocytes. "A defining feature of BRAF-mutant melanoma is the upregulation of proliferation-associated genes, such as MYC, CCND1, and E2F1, which synergistically fuel the unchecked growth of melanoma cells." (PMID 40872623, 2025). "Herein, we integrated a well-established E2F1-mediated epithelial-mesenchymal transition (EMT) map with transcriptomics data from E2F1-expressing melanoma cells to reconstruct a core regulatory network underlying aggressive melanoma." (PMID 37993971, 2023). "Recently, germinal CNVs of E2F1 have been proposed as genetic risk factor for testicular cancer and melanoma." (PMID 33691613, 2021). "This is the first study showing an association between germline E2F1 CNVs and melanoma development, suggesting a role for germline E2F1 gains as a contributing risk factor for melanoma." (PMID 31142321, 2019). "Increased levels of E2f1 are associated with melanomas, while reduced levels precipitate melanoma cell death, strongly suggesting that E2f1 could be a diagnostic melanoma biomarker." (PMID 35847038, 2022). "Abnormal expression of E2F1 is common in malignancy that are associated with poor patient survival prognosis, such as bladder cancer, non-small cell lung cancer, prostate cancer and melanoma." (PMID 35440106, 2022). "This study suggests a potential role of CNV in tumorigenesis as we found an association between germline E2F1 CNV and melanoma, however, further studies are needed in order to determine whether the additional E2F1 copy was acquired de novo or inherited." (PMID 31142321, 2019). "In addition to an increased risk for testicular cancer, subjects with altered germline E2F1 copies are potentially at risk of developing also melanoma, since E2F1 was also found in multiple copies in many melanoma cases." (PMID 31142321, 2019). "Therefore, subjects with multiple constitutive copies of E2F1 are at greater risk of developing melanoma when exposed to heat." (PMID 31142321, 2019). "Interestingly, in this study we demonstrate that heat stress stimulate the expression of E2F1 mRNA in melanoma cell line which further supports its role as potential risk factor for melanoma." (PMID 31142321, 2019). "The identification of downstream targets of heat inducing E2F1 activity in melanoma could provide further insight on the underlying molecular pathways that lead to the development of this cancer." (PMID 31142321, 2019). "Moreover, there are some evidences that E2F1 exhibit complex effect on melanoma cells controlling targets associated with primary or metastatic phenotype, such as hTERT and ASK/Dbf432." (PMID 30302012, 2018). "In addition, there are multiple targets of MYC, LEF1, and E2F1 that are also associated with poor outcomes for melanoma patients." (PMID 29666373, 2018). "Over-expression of E2F1 is associated with the development of a variety of tumors, and the increased copy number of E2F1 is known to be associated with over-expression of the gene in melanoma and cervical cancer." (PMID 26360582, 2015). "Having in mind that metastasis is linked with the activation of E2F1-governed GRNs, we applied a transcriptomics-aided bioinformatics workflow, followed by virtual drug screening to comprehensively characterize novel therapeutic targets in melanoma and predict their corresponding drug inhibitors." (PMID 37993971, 2023). "Using a CRISPR-Cas9-engineered model of melanoma initiation, the authors identified a direct signaling pathway where loss of CDKN2A leads to the activation of E2F1, which upregulates the lineage-restricted transcription factor BRN2." (PMID 41596618, 2026). "E2F1 plays a critical role in cell cycle regulation and has been established as an oncogene in melanoma cells." (PMID 41463281, 2025). "Among downregulated genes after ICG-001 treatment, BIRC5, EZH2, E2F1, and other oncogenes related to melanoma were found." (PMID 41227355, 2025).
melanoma (continued). "Consistently, the clinical data revealed that melanoma with abundant E2F1, STAT3 and IL-6 preferentially induce and maintain infiltration of Th2, while simultaneously blocking Th1 cells." (PMID 39544930, 2024). "Consistently, upregulation of E2F1 and IL-6 positively correlates with tumor infiltration of immunosuppressive Th2 cells in melanoma patients." (PMID 39544930, 2024). "H2A.Z2 enhances tumor sensitivity to drugs by gene transcriptional regulation for E2F1 in malignant melanoma." (PMID 39199381, 2024). "Following melanoma and endothelial cells’ co-culture, we also demonstrated an increased expression of the stem cell markers E2f1 and c-Myc in A375, and this up-regulation was prevented by TDO inhibition." (PMID 38794128, 2024). "Data-based simulations revealed that high levels of E2F1 in melanoma cells trigger autoactivation and a paracrine positive feedback loop with CD4+ T cells via secretion of IL-6 to the tumor niche to generate an inflammatory secretome." (PMID 39544930, 2024). "STAT3 was clearly recovered from E2F1 immunoprecipitates of whole melanoma cell lysates, whereas knockdown of E2F1 resulted in decreased binding of STAT3." (PMID 39544930, 2024). "Consistent with our previous data, the dramatically elevated IL-6 levels measured in high-E2F1 melanoma cocultures substantially decreased under E2F1-KD." (PMID 39544930, 2024). "To explore E2F1’s role in immune regulation in presence of aggressive melanoma cells, we established a coculture system and utilized transcriptome and cytokine arrays combined with bioinformatics and structural modeling." (PMID 39544930, 2024). "We demonstrate that high levels of E2F1 in melanoma cells disrupt the balance regulated by various cytokines/interleukins such as IL-6." (PMID 39544930, 2024). "We used high-E2F1 vs. E2F1-KD melanoma cell lines grown as monocultures or together with either CD4+ or CD8+ T cells from healthy donors." (PMID 39544930, 2024). "For gene expression analyses, we used a human melanoma tissue culture model comprising different cell lines with characteristic invasive/metastatic potential that show a positive correlation between E2F1 levels and cell motility." (PMID 39544930, 2024). "In fact, inhibition of E2F1 has been reported to decrease the metastatic potential of melanoma cells, pointing out the importance of E2F1 de-regulation not only in cancer cells’ proliferation but also in melanoma invasion." (PMID 38794128, 2024). "Our simulations suggest that high levels of IL-6 secretion by melanoma cells can be either achieved through high levels of E2F1, high levels of STAT3, or moderate levels of both TFs." (PMID 39544930, 2024). "We investigated the immunomodulatory properties of the E2F1-induced melanoma secretome in an indirect coculture system with healthy donor-derived CD4+ and CD8+ T cells." (PMID 39544930, 2024). "BRD2 together with E2F1 bind to E2F target genes in a H2A.Z.2-deposition dependent manner, in turn promote proliferation of melanoma cells." (PMID 38542118, 2024). "Amplification of the E2F1 gene has been observed in melanoma cell lines (compared to normal melanocytes) and also in melanoma metastases localized in lymph nodes." (PMID 38982214, 2024). "Herein, aided by in silico workflows, we sought to predict efficient and safe compounds that either alone or in combination prevent melanoma progression by specifically targeting components of the prometastatic E2F1-governed GRNs in melanoma." (PMID 37993971, 2023). "Over the past years, we and others have demonstrated that in addition to these driver events, melanoma progression is catalyzed by the abundant expression of E2F1, a member of the E2F transcription factor family." (PMID 37993971, 2023). "E2F1 is overexpressed in melanoma, and its inhibition initiates cell cycle arrest and apoptosis, as well as increasing the sensitivity of the melanoma cells to BRAF inhibitors." (PMID 38023136, 2023).
melanoma (continued). "The E2F1 map and the previously used workflow were applied to identify a key functional module (core regulatory network) in melanoma." (PMID 37993971, 2023). "Here, we utilized the workflow and the E2F1 map to identify key network motifs and critical molecular interactions that drive a highly invasive melanoma cell phenotype." (PMID 37993971, 2023). "We used our previously published network-based approach to construct a melanoma-specific regulatory core from the comprehensive E2F1 GRN." (PMID 37993971, 2023). "With the computational pipeline used in this study, we were successful in the identification of key protein signatures (AKT1 and MDM2) in melanoma from a core regulatory network that is based on a published E2F1 interaction map." (PMID 37993971, 2023). "The 12 TFs that were inferred to regulate NK and T cells activation in these modules are shown as follows: Module M1 contained the regulators IRF1, STAT1, SPI1, FLI1, IRF7, and E2F1, which are essential regulators for C4 Melanoma CORO1A." (PMID 37435067, 2023). "We and others demonstrated that progression of cancers such as melanoma, breast, and bladder cancer is catalyzed by the abundant expression of E2F1 and E2F1-mediated activation of downstream pro-metastatic gene regulatory networks (GRNs)." (PMID 36678712, 2022). "For example, RHAMM serves as a co-activator for the E2F1 transcription factor to mediate the transcription of fibronectin in melanoma cells." (PMID 36033439, 2022). "E2F1 and its interacting coregulators are important therapeutic targets to combat melanoma metastasis." (PMID 36678712, 2022). "A key player in melanoma is E2f1, a member of the E2f family of transcription factors involved in cell cycle regulation." (PMID 35847038, 2022). "In general, E2F1 serve as a tumor promoter in various tumors via activating the expression of oncogenes, for example, melanoma, lung cancer, liver cancer, renal cancer, colorectal cancer and so on." (PMID 35440106, 2022). "Conversely, depletion of SUV39H1 in melanoma cells leads to RB1 activation and reduced E2F1 transcriptional activity, inhibiting melanoma development." (PMID 35163453, 2022). "In search of relevant vulnerabilities underlying melanoma metastasis in conjunction with the TME, the cellular transcription factor E2F1 was identified as a key inducer of cancer cell dissemination." (PMID 36678712, 2022). "Consistent with the GSEA, Tbx2 depletion using three different siRNAs in mouse B16 melanoma cells led to a strong reduction of E2f1 protein expression." (PMID 34819350, 2021). "Strikingly, KLF4 was previously reported to be as the direct downstream target in the E2F1-mediated pro-tumorigenic of melanoma." (PMID 33726845, 2021). "KLF4 and Nanog were reported to be downstream target in the E2F1-mediated pro-tumorigenic of melanoma and self-renewal of hepatocellular CSCs." (PMID 33726845, 2021). "We determined that ASAH1 was overexpressed in a large percentage of melanoma cells and regulated by transcription factor E2F1 in a mitogen-activated protein (MAP) kinase pathway-dependent manner." (PMID 33766731, 2021). "E2F1 was the only transcription factor that was downregulated after vemurafenib treatment in both melanoma cell lines." (PMID 33766731, 2021). "E2F1, a transcription factor with diverse roles in apoptosis and the cell cycle, is upregulated in BRAFi-resistant melanoma and increases the expression of insulin-like growth factor 1 receptor (IGF-1R)." (PMID 33807778, 2021). "miRNA-224-5p can be regulated by E2F1 to drive EMT through TXNIP downregulation in melanoma, and it can inhibit uveal melanoma cell proliferation, migration, and invasion by targeting PIK3R3/AKT3." (PMID 32993558, 2020). "E2F1 is one of the most important and best characterized members of the E2F family in melanoma and known to activate AKT cell survival pathway." (PMID 32854238, 2020).
melanoma (continued). "E2F1 belongs to a family of heterodimeric transcription factors and inhibition of E2F1 activity increased melanoma cell senescence and death for cancer therapy." (PMID 31968672, 2020). "Another remarkable cooperative therapeutic benefit was also noticed due to the repression of E2F1 in aggressive melanoma and lung cancer cell lines." (PMID 32854238, 2020). "Another E2F family member, E2F5, similar to E2F1, is an oncogenic cell cycle regulator that is also found to be amplified in numerous tumors, including melanoma." (PMID 32722415, 2020). "According to another report, miR-205 decreased cellular proliferation in melanoma by regulating AKT phosphorylation through E2F1 inhibition." (PMID 32854238, 2020). "The transcription factor E2F1 is crucial for melanoma progression through directly transactivating the GABRE gene that expresses miR-224/miR-452." (PMID 32010624, 2019). "These gains were absent in individuals not affected by melanoma, whereas all subjects with multiple copies of E2F1 had melanoma." (PMID 31142321, 2019). "pRB expression and pRB/E2F1 interaction were significantly decreased in relapse melanoma lesions compared to baseline." (PMID 30899440, 2019). "E2F1 CNV was measured in genomic DNA isolated from blood of 552 patients diagnosed with melanoma and 520 healthy subjects using TaqMan Copy Number Assays." (PMID 31142321, 2019). "In this study we report that germline gains of E2F1 also occur in a relevant number of melanoma patients." (PMID 31142321, 2019). "Since germline copy number variations (CNVs) have been associated with increased susceptibility to different types of cancer, the aim of our study was to assess germline E2F1 CNV in melanoma patients." (PMID 31142321, 2019). "The gene encoding for E2F1 transcription factor, which maps on chromosome 20, is found in multiple copies in both melanoma specimens and melanoma cell lines, resulting in the overexpression of the E2F1 protein." (PMID 31142321, 2019). "E2F1 mRNA expression was also evaluated by RT-qPCR in the melanoma cell line, SK MEL 267, before and after exposure to heat stress." (PMID 31142321, 2019). "Although most of patients suffering from melanoma also harboured two copies of E2F1, a significant portion (1.6%, 9/552) had more than the two canonical copies of the gene." (PMID 31142321, 2019). "We found that patients diagnosed with melanoma (1.6%, 9/552) harboured frequently altered germline E2F1 copies compared to healthy subjects (0%, 0/520)." (PMID 31142321, 2019). "A recent study showed that an inhibition of E2F1 leads to increased cell death in melanoma cells, even if they are resistant to BRAF-inhibitors." (PMID 31888467, 2019). "Our study has demonstrated that inhibition of E2F1 (transcription factor from E2F1 family) is effective in decreasing melanoma cell viability in both sensitive and resistant metastatic melanoma cells." (PMID 29743521, 2018). "miR-205-5p is known to be down-regulated in melanoma and its expression inversely correlated with that of E2F1." (PMID 29661169, 2018). "By probing a panel of primary and metastatic melanoma cell lines and human melanocytes, we found that E2F1 is also strongly expressed in different melanoma cell lines and in melanoma cells freshly isolated from patients." (PMID 29743521, 2018). "E2F1 is a crucial mediator of Hh signaling, and it is required for melanoma cell proliferation and xenograft growth induced by activation of the Hh pathway." (PMID 29849100, 2018). "Taken together, E2F1 loss enhances sensitivity of melanoma cells to targeted therapies and induces the death of BRAF inhibitor-resistant melanoma cells." (PMID 29743521, 2018). "Depletion of E2F1 using small interfering RNA (siRNA) or pharmacological blockade of E2F activity further increased melanoma cell death and senescence, both in vitro and in vivo." (PMID 29743521, 2018).
melanoma (continued). "In our system, we confirm that inhibition of E2F1 using siRNA in melanoma cells leads to apoptotic cell death." (PMID 29743521, 2018). "Inhibition of E2F1 activity further increased melanoma cell death and senescence, both in vitro and in vivo." (PMID 29743521, 2018). "In parallel, we observed that E2F1 inhibition is also able to induce DNA damage in A375-resistant melanoma cells as indicated by increased expression of γH2AX." (PMID 29743521, 2018). "To further understand the molecular mechanisms linking E2F1 and melanoma cell viability, we measured cell cycle phases by propidium iodide (PI) labeling in A375 melanoma cells." (PMID 29743521, 2018). "We also demonstrated that E2F1 inhibition in melanoma cells induces a cellular phenotype displaying several hallmarks of senescence, such as larger but flatter cells with more granulation and increased senescence-associated-β-gal (SA-β-Gal) activity." (PMID 29743521, 2018). "While E2F proteins, in particular E2F1, have emerged as critical players in melanoma development, our mechanistic understanding of its regulation and function remains limited." (PMID 29743521, 2018). "Using immunohistological analysis of human biopsies, we detected E2F1 staining in primary melanoma, with a robust expression in metastatic melanoma." (PMID 29743521, 2018). "Intriguingly, the inhibition of E2F1 induced loss of cell viability of sensitive and BRAF inhibitor-resistant melanoma cells." (PMID 29743521, 2018). "E2F1 inhibition decreased the viability of melanoma cells with acquired resistance to BRAF inhibitor through the induction of apoptosis and DNA damage." (PMID 29743521, 2018). "Flow cytometry experiments demonstrated that the inhibition of E2F1 led to an increase in size and the granularity of melanoma cells, which are morphological characteristics of cellular senescence." (PMID 29743521, 2018). "Knockdown of RTL1 in melanoma cells resulted in cell proliferation suppression; cell cycle arrest at G1 phase; and down-regulation of E2F1, CYCLIN D1, cyclin-dependent kinase 6 (CDK6) and c-MYC." (PMID 29285312, 2017). "Increased expression of E2f1 is a common feature of several types of cancers such as melanoma and HCC10." (PMID 26639898, 2015). "Due to the abolished binding of Rb to E1A, the subsequent release of E2F1 from the inhibitory E2F1-Rb complex is prevented, thus limiting the viral replication to cells with abnormal Rb control, which is commonly seen in melanoma." (PMID 25071017, 2014). "In a previous study it has been shown that eugenol inhibits cell proliferation in melanoma cells through inhibition of E2F1." (PMID 24330704, 2013). "Another mechanism of E2F1-induced invasiveness has been confirmed by the E2F1-epidermal growth factor receptor interaction with E2F1 in melanoma progression." (PMID 24023875, 2013). "Taken together, we provide a novel molecular mechanism by which oncongenic transcription factors, CREB and E2F-1, contribute to the metastatic phenotype of melanoma by negatively regulating AP-2α expression at the transcriptional level." (PMID 20805990, 2010). "Herein, we propose a potential mechanism by which CREB induces transcriptional repression of AP-2α during melanoma progression through upregulation of oncogenic E2F-1." (PMID 20805990, 2010). "Previous studies utilizing adenoviral-mediated transfection of E2F-1 genes induced apoptosis of melanoma cells, and an additional study revealed that E2F-1 suppressed cell growth while decreasing telomerase activity in the Tu-167 SCCHN cell line." (PMID 18366791, 2008). "Our studies strongly demonstrated that E2F-1 induces melanoma cell apoptosis via PUMA up-regulation and Bax translocation." (PMID 17263886, 2007).